APP (amyloid beta precursor protein)
Diseases named in the same sentence as APP in open-access papers (continued):
Sharing a sentence is not in itself a finding about the gene and the disease.
Alzheimer disease (continued). "Differentially expressed mRNAs in hippocampus of APP/PS1 transgenic mice with Alzheimer disease." (PMID 33221745, 2020). "Inhibition of PLA2 signaling may represent an important signaling pathway to target for the treatment of Alzheimer's disease, to reduce the amount of APP that is released from neurons and decrease the burden of accumulation of toxic amyloid plaques." (PMID 33584282, 2020). "Alzheimer’s disease is characterized by the accumulation of proteinous soluble and insoluble amyloid aggregates and fibrils of Aβ peptides, which result from the cleavage of APP through the amyloidogenic pathway." (PMID 32759666, 2020). "In the absence of Chr 21 trisomy, duplication of APP alone is a cause of early onset Alzheimer’s disease, making it likely that having three copies of APP is important in the development of AD and in DS." (PMID 33633844, 2020). "Recently, ligustilide has attracted widespread attention in the field of Alzheimer’s disease, owing to its capacity to reduce the levels of p-Tau, mutant APP, Aβ1-42 oligomers and monomers, ameliorate oxidative stress induced neuronal apoptosis, provide an effective neuroprotection." (PMID 32065782, 2020). "Altogether, these findings suggest that 37/67kDa LR modulation may represent a useful tool to control APP trafficking and Aβ levels with implications in Alzheimer’s disease." (PMID 33207563, 2020). "Guix and colleagues reported that TSPAN6 was increased in Alzheimer’s disease brains and promoted Aβ-peptide accumulation by affecting the autophagosome–lysosomal pathway and slowing down the degradation of Amyloid precursor protein (APP)–C-terminal fragments." (PMID 33343629, 2020). "In addition, three gene mutations are responsible for Alzheimer’s disease, including presenilin 1 (PSEN1), presenilin 2 (PSEN2) and amyloid precursor protein (APP), with presenilin 1 being the most common." (PMID 32085610, 2020). "Further investigation of ADAM9, AGAP2 and PSEN1 levels in human subjects with APP-related disorders could help in understanding Alzheimer’s disease and autism spectrum disorders." (PMID 32612155, 2020). "Since the role of the retina in Alzheimer’s disease is still widely disputed, the aim of this work was to provide a comprehensive overview of what can be observed in the retina of an APP/PS1 mouse model using multicontrast OCT and to compare this to histological results." (PMID 32042855, 2020). "Thus, Alzheimer’s disease phenotype-related accumulation of mutant amyloid beta precursor protein (APP) induces Parkin-dependent mitophagy in cultured human neurons and in the brain of Alzheimer’s patients." (PMID 32671064, 2020). "Although Alzheimer's disease is a multifactorial disease, it is characterized by the increased generation and/or accumulation of amyloidogenic peptides (particularly Aβ), which are derived from the proteolysis of APP." (PMID 32879651, 2020). "It cleaves more than a hundred type-I transmembrane substrates including Notch (important for development and cancer), ErbB4 (involved in breast cancer), and the Amyloid Precursor Protein (APP), whose cleavage product is the toxic amyloid-β, a major hallmark in Alzheimer’s disease." (PMID 32631487, 2020). "More recently, in a model of Alzheimer’s disease using amyloid precursor protein (APP) overexpressed neuroblastoma cells, newly synthesised imidazoquinazolinone TSPO ligands were able to reduce oxidative injury by decreasing ROS generation in response to H2O2 stimulation." (PMID 32102369, 2020). "A large body of evidence indicates that dysregulation of cerebral biometals (Fe, Cu, Zn) and their interactions with amyloid precursor protein (APP) and Aβ amyloid may contribute to the Alzheimer’s disease (AD) Aβ amyloid pathology." (PMID 32155778, 2020). "Compounds that improve M1 mAChR coupling to Gαq and away from PLA2 may yield Alzheimer's disease modifying benefits, by decreasing APP secretion, amyloid-β production and Tau hyperphosphorylation." (PMID 33584282, 2020).
Alzheimer disease (continued). "There is compelling evidence supporting an early and central role for Ca2+ dysregulation in the pathogenesis of Alzheimer’s disease (AD), including sporadic AD, whose etiology is not related to mutations in presenilins or APP." (PMID 32012922, 2020). "Potential pathogenic factors, other than well-known APP, APOE4, and PSEN, can be further identified from transcriptomics studies of differentially expressed genes (DEGs) that are specific for Alzheimer’s disease (AD), but findings are often inconsistent or even contradictory." (PMID 32231518, 2020). "Research on Alzheimer's disease (AD), using the APP/PS1 mouse model and 13C-NMR metabolomics, has revealed a decrease in the lactate–alanine shuttle in the brain, limiting the source of ammonia nitrogen from alanine that is used in the glutamate–glutamine cycle." (PMID 32499676, 2020). "Moreover, the present study identified APP, which plays key roles during Alzheimer’s disease progression, as the most highly connected hub gene of the M1 module." (PMID 33086708, 2020). "Compelling pre-clinical and clinical evidence supports the involvement of the LC-NE system in Alzheimer's Disease (AD) via the influence of Ars on the processing of amyloid precursor protein (APP), dysregulation of the stress-signaling axis, and exacerbation of neuroinflammation." (PMID 33584368, 2020). "Alzheimer’s disease (AD) is pathologically defined by extracellular accumulation of amyloid-β (Aβ) peptides generated by the cleavage of amyloid precursor protein (APP), strings of hyperphosphorylated Tau proteins accumulating inside neurons known as neurofibrillary tangles (NFTs) and neuronal loss." (PMID 33061903, 2020). "APP is proteolytically cleaved by secretases, resulting in a series of biologically active fragments, including the amyloid-β peptide characterizing the pathogenesis of Alzheimer’s disease (AD) and cerebral amyloid angiopathy (CAA)." (PMID 33228083, 2020). "The biochemical phase of Alzheimer’s disease (AD) is characterized in part by the accumulation and aggregation of the neurotoxic amyloid-β (Aβ) peptide, which is generated by sequential proteolytic processing of the Amyloid Precursor Protein (APP)." (PMID 31915042, 2020). "Finally, in the APP/PS1 mouse model of Alzheimer’s disease (AD), the stabilization, expansion, and closure of the fusion pore was faster, but the secretion was attenuated." (PMID 32178443, 2020). "The amyloid precursor protein (APP) is a key player in Alzheimer’s disease (AD) pathogenesis." (PMID 32327470, 2020). "Alzheimer’s disease (AD) is characterized by the formation of intracellular aggregate composed of heavily phosphorylated tau protein and extracellular deposit of amyloid-β (Aβ) plaques derived from proteolysis cleavage of amyloid precursor protein (APP)." (PMID 33374126, 2020). "tPA also initiates the degradation of amyloid-β (Aβ), resulting in decreasing level of Aβ derived from amyloid precursor protein (APP), which may delay pathogenic progression of Alzheimer's disease (AD)." (PMID 31440383, 2019). "Importantly, the palmitoylation of amyloid precursor protein (APP) and huntingtin are implicated in Alzheimer’s disease and Huntington’s disease pathogenesis, respectively." (PMID 30946007, 2019). "In addition to the devastating symptoms of dementia, Alzheimer’s disease (AD) is characterized by accumulation of the processing products of the amyloid-β (Aβ) peptide precursor protein (APP)." (PMID 30470799, 2019). "Familial Alzheimer’s disease (FAD)-associated presenilin 1 (PS1) serves as a catalytic subunit of γ-secretase complex, which mediates the proteolytic liberation of β-amyloid (Aβ) from β-amyloid precursor protein (APP)." (PMID 30682043, 2019).
Alzheimer disease (continued). "In summary, our results suggest a role for APPL and its proteolytic cleavage sites in retrograde trafficking, thus our findings are of relevance to the understanding of the endogenous role of APP as well as to the development of therapeutic treatments of Alzheimer’s disease." (PMID 31354437, 2019). "In our preliminary data, we could verify this trend in mRNA expression in the brain capillaries of an Alzheimer’s disease mouse model (APP/PS1 transgenic mouse model)." (PMID 31610812, 2019). "In addition to its presence in Alzheimer’s disease, APP phosphorylation has also been found to occur during cellular stress and mitosis and in differentiated neurons." (PMID 31892243, 2019). "Indeed, a small molecule TrkA partial agonist called D3 normalized TrkA signals and improved memory in cognitive impairment models of ageing and an APP mouse model of Alzheimer’s disease." (PMID 31233568, 2019). "APP or amyloid-β precursor protein is a transmembrane protein shown to be important for the formation and transmission of synapses of neurons in culture and crucial to the pathology of Alzheimer’s disease." (PMID 30792836, 2019). "The levels of tau and APP were reduced in microvesicles of Alzheimer’s disease patients." (PMID 31068645, 2019). "APP represents a key axonal transport cargo in Alzheimer’s disease." (PMID 31806024, 2019). "Interestingly, we detected an enrichment of a neurodegenerative disease signature, as previously reported, and we identified APP, which is involved in Alzheimer’s disease, as a node with a high number of interactions within the PPI network associated with CM." (PMID 31666081, 2019). "APP participates in the progression of Alzheimer’s disease and cancer." (PMID 31123603, 2019). "The amyloid (Aβ) hypothesis of Alzheimer’s disease (AD) has primarily been driven by the observation that genetic variability that alters amyloid precursor protein (APP) metabolism increases de position of Aβ1." (PMID 31270419, 2019). "Knock-in (KI) mouse models of Alzheimer’s disease (AD) that endogenously overproduce Aβ without non-physiological overexpression of amyloid precursor protein (APP) provide important insights into the pathogenic mechanisms of AD." (PMID 30894120, 2019). "The human Alzheimer disease array revealed that Cpn infection at each timepoint post-infection altered the expression of several genes directly and indirectly involved with the development of AD pathology through APP processing and tau-related mechanisms." (PMID 30786875, 2019). "Chromosome 21 carries the APP gene, so that the three copies of chromosome 21 may be important in the DS and Alzheimer’s disease connection through increased APP and beta amyloid." (PMID 29587359, 2018). "Moreover, targeting the aspects of Alzheimer’s disease (AD) other than cleavages of the APP by β and α secretases should have analogous impacts in both FAD and SAD." (PMID 29865246, 2018). "Autosomal dominant (familial) Alzheimer's disease, due to mutations in presenilin 1 (PSEN1), presenilin 2 (PSEN2), or amyloid precursor protein (APP) genes, shares many features, both pathophysiologically and clinically, with the much more common sporadic form of the disease." (PMID 29413314, 2018). "As PrPC is associated with prion diseases as well as Alzheimer's disease (through its interactions with APP and Aβ oligomers), knowledge gained from these studies will accelerate/enhance the development and screening of prion disease and Alzheimer's disease therapeutics." (PMID 29358166, 2018). "The outcomes from these experiments showed that the high charged particle radiation may rise Aβ plaque pathology in APP/PS1 mouse model of Alzheimer’s disease." (PMID 29867445, 2018). "In this study, we employed 7-month-old APP/PS1 mice to explore whether LIG is able to protect against Alzheimer's disease progression." (PMID 30079347, 2018). "APP is one of the central proteins involved in CNS pathology in Alzheimer's disease (AD)." (PMID 29922220, 2018).
Alzheimer disease (continued). "In models of Alzheimer's disease, increased nNOS–CAPON interaction was detected after treatment with amyloid‐β in vitro, and a similar change was found in the hippocampus of APP/PS1 mice (a transgenic mouse model of Alzheimer's disease), compared with age‐matched background mice in vivo." (PMID 29577585, 2018). "The synaptic pathology of Alzheimer's disease may be able to be modified if we could control the synaptic localization of APP." (PMID 30226901, 2018). "In this study, we examined whether the inhibition of the synaptic localization of APP affects the phenotypes of the Drosophila model of Alzheimer's disease." (PMID 30226901, 2018). "Although whether the synaptic pathology observed in Alzheimer's disease is attributed to the molecular function of APP at the synapse remains to be elucidated, the synaptic pathology may be modified by controlling the synaptic transport of APP." (PMID 30226901, 2018). "In particular, a key study demonstrated that the mRNA and protein levels for ColVI are elevated in the hippocampal neurons of Alzheimer's disease patients, as well as in a commonly used transgenic mouse model of Alzheimer's disease expressing mutant human amyloid precursor protein (APP)." (PMID 29728408, 2018). "Together with others, our study suggests that defects in APP function might be directly related not only to Alzheimer's disease (AD), but also to other neurodegenerative diseases involving muscle denervation, such as ALS." (PMID 29899726, 2018). "Having three copies of chromosome 21 genes other than APP may influence the development of Alzheimer’s disease in people who have Down syndrome." (PMID 29945247, 2018). "Interestingly, APP/PS1 Alzheimer’s disease mice whose astrocytes chronically overexpress IL-1β have reduced hippocampal amyloid load, although contextual and spatial memory impairments in control animals were evident." (PMID 30044427, 2018). "Delta-secretase cleaves both APP and Tau, and contributes to Alzheimer’s disease-like pathology." (PMID 29725016, 2018). "The past two decades have seen great enthusiasm for the Amyloid Hypothesis of Alzheimer’s disease that posits a pathological role for the Aβ peptide cleaved from the AMYLOID BETA A4 PRECURSOR PROTEIN (APP)." (PMID 30150923, 2018). "Triplication of APP, a gene on chromosome 21, is sufficient to cause early-onset Alzheimer’s disease in the absence of Down syndrome." (PMID 29945247, 2018). "Furthermore, The APP/PS1 mice (a mouse model for Alzheimer’s disease) with NLRP3 knockout are protected from spatial memory impairment and have a decreased Aβ plaque burden." (PMID 29665808, 2018). "Mutations that are established to be pathogenic in APP and PSEN1 were found in either a clinical DLB case; or in pathologically confirmed DLB cases, of which 69% of the cohort also met pathological criteria for Alzheimer’s disease." (PMID 30097731, 2018). "Defects in the endolysosomal pathway have been observed in Alzheimer’s disease (AD) models, resulting in aberrant release of Amyloid Precursor Protein (APP) species in exosomes, allowing for elimination of lysosomal contents that cannot be efficiently degraded." (PMID 30174585, 2018). "Since the polymorphism UBQ-8i (rs12344615) in UBQLN1 has been associated with increased risk of late-onset Alzheimer’s disease (LOAD) and differences in UBQLN1 exon 8 splicing, we asked whether APP/UBQLN1 co-splicing was modulated by UBQ-8i." (PMID 30545302, 2018). "Since MAPT becomes hyperphosphorylated and aggregates in the neurons of Alzheimer’s disease brains, we would expect this to reduce the available APP on the neuronal plasma membrane and so reduce iron export in aged neurons showing Alzheimer’s disease pathology." (PMID 30150923, 2018).
Alzheimer disease (continued). "To take an unbiased approach and investigate if triplication of genes other than APP can modulate the development of Down syndrome–Alzheimer’s disease in vivo, we crossed a model of Down syndrome that is aneuploid for chromosome 21 with a mouse that deposits amyloid-β in the brain." (PMID 29945247, 2018). "The source of fermented milks cultured with various probiotic strains could improve amyloid precursor protein (APP) metabolism in Alzheimer’s disease." (PMID 30217053, 2018). "At the experimental level, long-term caffeine treatment has been demonstrated to ameliorate cognitive impairment in animal models of Alzheimer disease: βA-injection mouse models and transgenic mouse models including APP, APP/PS1, and more recently in a tau transgenic model." (PMID 29497377, 2018). "Duplication of APP alone, in the absence of chromosome 21 trisomy, is a cause of early onset Alzheimer’s disease making it likely that three copies of APP are important in the development of Down syndrome–Alzheimer’s disease." (PMID 29945247, 2018). "The amyloid cascade hypothesis posits that the initiating event in Alzheimer’s disease (AD) is the aggregation and deposition of the β-amyloid (Aβ) peptide, which is a proteolytic cleavage product of the amyloid precursor protein (APP)." (PMID 29615128, 2018). "APP is a prominent candidate gene for Alzheimer’s disease (AD)." (PMID 30545302, 2018). "Recently, we discovered that seizures and epileptiform activity also robustly increased ∆FosB expression in the hippocampus of a transgenic mouse model of Alzheimer’s disease (AD) expressing mutant human amyloid precursor protein (APP, line J20) as well as in pharmacological models of epilepsy." (PMID 29408867, 2018). "The amyloid cascade hypothesis postulates that extracellular liberation of Aβ due to aberrant amyloid precursor protein (APP) processing plays the key role in Alzheimer’s disease (AD) pathology." (PMID 29301548, 2018). "Despite its key role in the molecular pathology of Alzheimer’s disease (AD), the physiological function of amyloid precursor protein (APP) is unknown." (PMID 28210211, 2017). "So the transgenic APP/PS1 mice can well simulate human Alzheimer's disease of graduated progress." (PMID 29422937, 2017). "In the amyloidogenic pathway associated with Alzheimer disease (AD), the amyloid precursor protein (APP) is cleaved by β‐secretase to generate a 99‐aa C‐terminal fragment (C99) that is then cleaved by γ‐secretase to generate the β‐amyloid (Aβ) found in senile plaques." (PMID 29018038, 2017). "On one hand, overexpression of APP, which is often used to model Alzheimer’s disease, may alter dendritic spines independently of typical Alzheimer’s disease pathology." (PMID 28539872, 2017). "Moreover, celastrol was also found to be a potent Aβ lowering compound by reducing the β-cleavage of APP (Amyloid precursor protein) in a transgenic mouse model of Alzheimer’s disease." (PMID 28509859, 2017). "The role of Vit C in AD disease was studied in APP/PSEN1 mice carrying human AD mutations in the amyloid precursor protein (APP) and presenilin (PSEN1) genes (transgenic mouse model of Alzheimer’s disease) with partial ablation of vitamin C transport in the brain." (PMID 28654017, 2017). "On the other hand, this might cancel the vitamin D-prevented amyloid-beta cytotoxicity, a pathological marker of Alzheimer's disease, due to the induced amyloid precursor protein (APP) phosphorylation by activated JNK in neurons." (PMID 28427151, 2017). "Our results suggest a potential benefit to screening nonfamilial Alzheimer disease (AD) cases with onset before 50 y for APP, PSEN1, and PSEN2 mutations." (PMID 28350801, 2017). "The accumulation of amyloid beta (Aβ) peptide (Amyloid cascade hypothesis), an APP protein cleavage product, is a leading hypothesis in the etiology of Alzheimer's disease (AD)." (PMID 28985224, 2017).